C11orf58 (chromosome 11 open reading frame 58)
Synonyms: SMAP; Hero20; IMAGE145052
Tractability: PROTAC: UniProt records ubiquitination sites on it; ubiquitination databases record sites on it.
Gene: Protein-coding gene on chromosome 11 (16,613,132 to 16,758,340, forward strand). Ensembl gene ENSG00000110696.
Subcellular location (Human Protein Atlas): Endoplasmic reticulum; Nucleoplasm
Gene Ontology:
Cellular component: nucleus
Genetic constraint (gnomAD): Loss-of-function variants: 2 observed, 14.15 expected, observed/expected ratio (o/e) 0.14, 90% interval 0.057 to 0.44. The upper end of that interval is the gene's LOEUF score, 0.44, which puts it in group 1 of 6, group 1 being the genes least tolerant of losing a copy. Missense variants: 113 observed, 169.47 expected, observed/expected ratio (o/e) 0.67, 90% interval 0.57 to 0.78. Synonymous variants: 53 observed, 56.38 expected, observed/expected ratio (o/e) 0.94, 90% interval 0.75 to 1.18.
Homologues: Orthologues: macaque C14H11orf58 (99% identical), dog C21H11orf58 (99% identical), rabbit C11orf58 (99% identical), guinea pig C11orf58 (97% identical), mouse 1110004F10Rik (95% identical), rat C1h11orf58 (94% identical), pig C11orf58 (92% identical), tropical clawed frog c4h11orf58 (58% identical), zebrafish zgc:56106 (51% identical).
Diseases named in the same sentence as C11orf58 in open-access papers:
C11orf58 is named in the same sentence as 11 diseases in open-access papers, as found by Europe PMC text mining. Sharing a sentence is not in itself a finding about the gene and the disease. The quoted sentences say what the papers report.
Stroke (1 paper, 2024). Sudden impairment of blood flow to a part of the brain due to occlusion or rupture of an artery to the brain. "The genetic variants associated with stroke risk and C11orf58 reveal diverse impacts on transcription factor (TF) binding and biological processes." (PMID 39595169, 2024). "Future prospects for this study could include analyzing C11orf58 gene expression profiles and DNA methylation levels at different stages of stroke, such as the acute and recovery phases, to gain a deeper understanding of C11orf58’s role in stroke." (PMID 39595169, 2024).
C11orf58 also shares sentences with these, for which no sentence is quoted: Arrhythmia (1 paper); atherosclerosis (1); atrial fibrillation (1); cancer (1); Cardiovascular Disease (1); cerebrovascular diseases (1); dyslipidemia (1); high blood pressure (1); Obesity (1); small artery occlusion (1).